ANAPC1 (anaphase promoting complex subunit 1)
Description:
Component of the anaphase promoting complex/cyclosome (APC/C), a cell cycle-regulated E3 ubiquitin ligase that controls progression through the cell cycle. APC/C acts by mediating ubiquitination and subsequent degradation of target proteins: it mainly mediates the formation of 'Lys-11'-linked polyubiquitin chains and, to a lower extent, the formation of 'Lys-48'- and 'Lys-63'-linked polyubiquitin chains. APC/C catalyzes assembly of branched 'Lys-11'-/'Lys-48'-linked branched ubiquitin chains on target proteins. APC/C is activated by CDC20 in the metaphase/anaphase transition of the cell cycle, targeting the degradation of cyclin B and securin. APC/C is regulated by the mitotic checkpoint complex (MCC), which inhibits APC/C and delays chromosome segregation.
Synonyms: APC1; TSG24; MCPR
Tractability: PROTAC: ubiquitination databases record sites on it; its protein half-life has been measured.
Gene: Protein-coding gene on chromosome 2 (111,611,639 to 111,884,690, reverse strand). Ensembl gene ENSG00000153107.
Subcellular location (Human Protein Atlas): Vesicles
Pathways (Reactome):
Cell Cycle: APC-Cdc20 mediated degradation of Nek2A; APC/C:Cdc20 mediated degradation of Cyclin B; APC/C:Cdc20 mediated degradation of Securin; APC/C:Cdc20 mediated degradation of mitotic proteins; APC/C:Cdh1 mediated degradation of Cdc20 and other APC/C:Cdh1 targeted proteins in late mitosis/early G1; Autodegradation of Cdh1 by Cdh1:APC/C; Cdc20:Phospho-APC/C mediated degradation of Cyclin A; Conversion from APC/C:Cdc20 to APC/C:Cdh1 in late anaphase; Inactivation of APC/C via direct inhibition of the APC/C complex; Phosphorylation of the APC/C; Regulation of APC/C activators between G1/S and early anaphase; Separation of Sister Chromatids
DNA Replication: Assembly of the pre-replicative complex; CDK-mediated phosphorylation and removal of Cdc6
Cellular responses to stimuli: Senescence-Associated Secretory Phenotype (SASP)
Disease: Aberrant regulation of mitotic exit in cancer due to RB1 defects
Gene expression (Transcription): Transcriptional Regulation by VENTX
Immune System: Antigen processing: Ubiquitination & Proteasome degradation
Gene Ontology:
Molecular function: molecular adaptor activity
Biological process: anaphase-promoting complex-dependent catabolic process; protein branched polyubiquitination; protein K11-linked ubiquitination; protein K48-linked ubiquitination; metaphase/anaphase transition of mitotic cell cycle; regulation of meiotic cell cycle; regulation of mitotic cell cycle; protein ubiquitination
Cellular component: anaphase-promoting complex; cytosol; nucleoplasm; nucleus
Genetic constraint (gnomAD): Loss-of-function variants: 26 observed, 132.22 expected, observed/expected ratio (o/e) 0.2, 90% interval 0.14 to 0.27. The synonymous counts are far from expectation, so gnomAD's model fits this gene poorly and the ratio says little. Missense variants: 820 observed, 1,349.5 expected, observed/expected ratio (o/e) 0.61, 90% interval 0.57 to 0.64. Synonymous variants: 328 observed, 462.26 expected, observed/expected ratio (o/e) 0.71, 90% interval 0.65 to 0.78.
Gene-disease validity (ClinGen):
ClinGen rates the evidence that ANAPC1 causes each of these diseases.
Rothmund-Thomson syndrome type 1 (autosomal recessive): Moderate.
Homologues: Orthologues: chimpanzee ANAPC1 (99% identical), macaque ANAPC1 (98% identical), rabbit ANAPC1 (97% identical), pig ANAPC1 (97% identical), guinea pig ANAPC1 (96% identical), rat Anapc1 (93% identical), mouse Anapc1 (92% identical), dog ANAPC1 (81% identical), tropical clawed frog anapc1 (81% identical), zebrafish anapc1 (67% identical), Drosophila melanogaster shtd (35% identical), Caenorhabditis elegans mat-2 (18% identical).
Diseases named in the same sentence as ANAPC1 in open-access papers:
ANAPC1 is named in the same sentence as 33 diseases in open-access papers, as found by Europe PMC text mining. Sharing a sentence is not in itself a finding about the gene and the disease. The quoted sentences say what the papers report.
cataract (2 papers, 2019 to 2023). Partial or complete opacity of the crystalline lens of one or both eyes that decreases visual acuity and eventually results in blindness. "Moreover, cataracts were almost exclusively seen in individuals harboring variants in ANAPC1 and DNA2, in the former as the classical, juvenile form described in the first reports of RTS, and in the latter, as a congenital form, frequently associated with other ocular anomalies." (PMID 38021400, 2023). "In CC54, 5 genes (ANAPC1, RPIA, IGF2BP2, CYP2J2 and LRIG1) and 1 disease (Cataract) were extracted as a correlated set." (PMID 31345171, 2019).
HCMV infection (2 papers, 2018 to 2020). "Notably, this group contained the known HCMV restriction factors Sp100, MORC3, DAXX, and HLTF in addition to cell cycle regulating protein ANAPC1, all of which have been reported to be degraded during HCMV infection by ourselves and others." (PMID 33585265, 2020). "We report that ANAPC2, in addition to ANAPC1, 4, and 5, is degraded early during HCMV infection, suggesting that inhibition of these proteins may be of particular importance in subverting the host cell-cycle machinery during infection." (PMID 30122656, 2018).
osteosarcoma (2 papers, 2021 to 2023). A usually aggressive malignant bone-forming mesenchymal neoplasm, predominantly affecting adolescents and young adults. "Genetic diagnosis in RTS is indispensable to confirm the specific subtype and its associated risks: juvenile cataracts are features of RTS1 (ANAPC1 gene), whereas a high risk of osteosarcoma is part of RTS2 (RECQL4 gene)." (PMID 35664819, 2021). "We showed that the expression of ANAPC1 is reduced in the bone and muscle tissue of osteoporosis patients and that ANAPC1 influences the processes of osteogenic differentiation of the human osteosarcoma cell line by downregulating RUNX2 during osteogenic differentiation." (PMID 37629076, 2023). "Here, we investigated the involvement of ANAPC1 in bone remodelling and the development of osteoporosis by analysing the expression of ANAPC1 in human bone and muscle tissue during osteogenic differentiation in human mesenchymal stem cells and by silencing a gene in human osteosarcoma cells." (PMID 37629076, 2023). "A pathogenic mutation in ANAPC1 leads to a genetic disorder, Rothmund–Thomson syndrome (OMIM number 618625), which mainly affects the skin but also the bones and has also recently been linked to an increased risk of osteosarcoma." (PMID 37629076, 2023). "Our results suggest that the silencing of ANAPC1 affects the expression level of RUNX2 in human osteosarcoma cells, but the mineralisation process is not hindered." (PMID 37629076, 2023). "Moreover, the silencing of ANAPC1 in human osteosarcoma (HOS) cells reduced RUNX2 expression, suggesting that ANAPC1 affects osteogenic differentiation through RUNX2." (PMID 37629076, 2023).
Rothmund-Thomson syndrome (2 papers, 2021 to 2022). "Rothmund-Thomson syndrome results from loss of functional RECQL4 or ANAPC1." (PMID 35359366, 2022). "In another study, decreased ANAPC1 transcript and corresponding APC1 protein levels results in Rothmund-Thomson syndrome that effects multiple organ systems." (PMID 34109183, 2021).
breast carcinoma (1 paper, 2024). "While other cell cycle-related proteins were downregulated in breast cancer cells exposed to CB agonists, ANAPC1 was upregulated in our study." (PMID 39527598, 2024).
Cluster headache (1 paper, 2022). A type of headache characterized by repeated attacks of unilateral pain lasting 15 to 180 minutes and associated with local autonomic signs. "Gene-based association testing also identified several possible additional loci, among these, ANAPC1 has also been identified in another cluster headache GWAS using gene-based analysis, with enriched expression in the brain, particularly neurons." (PMID 36404298, 2022).
corneal diseases (1 paper, 2019). "The TCF4 variant also strongly associates with CH and it is interesting to note that the TCF4 and ANAPC1 variants control almost the same quantitative corneal traits but have very different associations with corneal disease." (PMID 30894546, 2019).
glaucoma (1 paper, 2019). Increased pressure in the eyeball due to obstruction of the outflow of aqueous humor. "Furthermore, glaucoma risk is strongly associated with lower cell density, while for example the ANAPC1 variant that controls a quarter of the cell density variance does not associate directly with POAG or PACG." (PMID 30894546, 2019).
Insulin resistance (1 paper, 2021). Increased resistance towards insulin, that is, diminished effectiveness of insulin in reducing blood glucose levels. "Additionally, mindbomb E3 ubiquitin protein ligase 2 (MIB2), anaphase promoting complex subunit 1 (ANAPC1), and ELOC, Elongin C (TCEB1), are also involved in ubiquitination, which can affect the development of insulin resistance and MetS." (PMID 34516309, 2021).
multiple sclerosis (1 paper, 2018). A progressive autoimmune disorder affecting the central nervous system resulting in demyelination. "ANAPC1, a neurodevelopmental facilitator, and MERTK, a TAM receptor and multiple sclerosis risk gene, have also been proposed as candidate genes for the psychosis phenotype of 2q13 CNV carriers." (PMID 29603867, 2018).
osteoporosis (1 paper, 2023). A condition of reduced bone mass, with decreased cortical thickness and a decrease in the number and size of the trabeculae of cancellous bone (but normal chemical composition), resulting in increased fracture incidence. "The SNP rs17040773 is located in the intronic region of the ANAPC1 gene (p = 1.5 × 10−9) and was identified as an osteoporosis risk candidate in a GWAS meta-analysis of populations from around the world (North America, Europe, East Asia, and Australia)." (PMID 37629076, 2023). "The aim of the current study was to investigate the possible association between the ANAPC1 gene and the occurrence of osteoporosis." (PMID 37629076, 2023). "Indeed, our finding is supported by a previous study in patients with Rothmund–Thomson syndrome type 1, which showed that splicing mutations in the ANAPC1 gene resulted in decreased protein expression and skeletal abnormalities such as osteoporosis and bone fractures." (PMID 37629076, 2023). "Altogether, our results indicate that ANAPC1 plays a role in bone physiology and in the development of osteoporosis." (PMID 37629076, 2023). "Our results suggest that ANAPC1 plays a role in bone physiology and in the development of osteoporosis." (PMID 37629076, 2023). "In conclusion, our study shows a significant downregulation of ANAPC1 expression in the bone and muscle tissues of patients with osteoporosis, suggesting its possible involvement in the pathogenesis of this disease." (PMID 37629076, 2023). "We have shown that ANAPC1 expression is reduced in bone tissue from osteoporosis patients compared to bone tissue from healthy individuals." (PMID 37629076, 2023). "The observed downregulation of ANAPC1 expression in osteoporosis patients provides valuable insights into the molecular mechanisms underlying the development and progression of this disease." (PMID 37629076, 2023). "Our results show a significant decrease in ANAPC1 expression in patients diagnosed with osteoporosis compared to healthy individuals, suggesting a possible involvement in the pathogenesis of osteoporosis." (PMID 37629076, 2023). "Bones and muscles are endocrine organs that affect each other’s metabolism, and our results indicate the involvement of ANAPC1 in the pathological process of osteoporosis in muscle tissue." (PMID 37629076, 2023). "Here we investigate the involvement of the newly identified gene candidate ANAPC1 in bone physiology and pathology (osteoporosis and osteoarthritis)." (PMID 37629076, 2023). "Further studies are needed to elucidate the precise molecular mechanisms underlying the link between ANAPC1, RUNX2, and osteoporosis." (PMID 37629076, 2023). "To this end, we examined ANAPC1 expression in bone tissue from osteoporosis patients, osteoarthritic patients, and healthy patients." (PMID 37629076, 2023). "Since osteoporosis is a musculoskeletal disease, we hypothesized that the expression of ANAPC1 could also be altered in the muscle samples of osteoporotic subjects." (PMID 37629076, 2023).
retinal disease (1 paper, 2014). "The region contains 102 genes of which anaphase promoting complex subunit 1 (ANAPC1), c-mer proto-oncogene tyrosine kinase (MERTK) and nephronophthisis 1 (NPHP1) have been previously associated with retinal disease or retinal function." (PMID 25517981, 2014).
T-cell acute lymphoblastic leukemia (1 paper, 2024). Acute lymphoblastic leukemia of T-cell origin. "Anapc1 functions in the metaphase-to-anaphase transition in the cell cycle and has been associated with poor prognosis in T-cell acute lymphoblastic leukemia." (PMID 39080561, 2024).
cancer (2 papers, 2023 to 2024). A tumor composed of atypical neoplastic, often pleomorphic cells that invade other tissues. "One of the top missense driver genes identified by NBDep method is ANAPC1 which has not been reported in IntOGen and the literature research and it can be introduced as a novel cancer gene." (PMID 38195844, 2024).
infection (2 papers, 2018 to 2023). The state of being infected such as from the introduction of a foreign agent such as serum, vaccine, antigenic substance or organism. "Only one DEG was identified to be unique in B/Yamagata infection, ENSG00000204745, which is an anaphase-the promoting complex subunit (ANAPC1) pseudogene." (PMID 37766362, 2023).
tumor (2 papers, 2016 to 2020). "ANAPC1 expression level was significantly higher (P = 2 × 10−11), and ETS2 and SORBS1 expression level was significantly lower in tumor tissues than in non-malignant tissues (P = 5 × 10−4 and 1 × 10−8), respectively." (PMID 26893365, 2016). "To identify the functional effect of ANAPC1 rs3814026C>T, ETS2 rs461155A>G, SORBS1 rs7081076C>A and POLR2A rs2071504C>T, we evaluated the relationship between the genotypes of those SNPs and mRNA expression of each gene in tumor and paired non-malignant lung tissues." (PMID 26893365, 2016).
kidney disease (1 paper, 2025). "To validate the potential genes is functionally in kidney disease, we choose whole genes (CDC16, CDC20, CDC27, MAD2L1, ANAPC1, ANAPC7, BUB1B) from first highest score subnetwork obtained from Cytoscape MCODE plugin from upregulated genes PPI as hub genes." (PMID 40034749, 2025).
retinopathy (1 paper, 2014). "We obtained retinal tissue samples from four retinopathy affected SVs and two control dogs and used them to quantitate transcript levels of the four retinal candidate genes, MERTK, NPHP1, ANAPC1 and KRCC1 in the critical region." (PMID 25517981, 2014).
ANAPC1 also shares sentences with these, for which no sentence is quoted: Chronic colitis (1 paper); colorectal carcinoma (1); developmental delay (1); Erythema (1); genetic disorders (1); glioblastoma (1); glioma (1); hair disorders (1); leukemia (1); musculoskeletal disease (1); Obesity (1); psychosis (1); retinal degeneration (1); Rothmund-Thomson syndrome type 1 (1); schizophrenia (1).